MCU (mitochondrial calcium uniporter)
Diseases named in the same sentence as MCU in open-access papers (continued):
Sharing a sentence is not in itself a finding about the gene and the disease.
atherosclerosis (5 papers, 2021 to 2025). A disease characterized by the build-up of fatty material and calcium deposition in the arterial wall resulting in partial or complete occlusion of the arterial lumen. "This study is the first to report the association between the Pyk2/MCU pathway and atherosclerosis." (PMID 34026753, 2021). "Our findings unveil the previously unrecognized role of MAM-MICU1-MCU axis in cholesterol-induced mitochondrial calcium overload and atherosclerosis, indicating that MCU represents a promising therapeutic target for the treatment of atherosclerosis." (PMID 41329250, 2025). "In hepatic cells, MCU deficiency has been associated with increased lipid accumulation, and a murine atherosclerosis model demonstrated that MCU knockdown mitigated endothelial injury, further implicating the MCU complex in atherogenesis." (PMID 40422231, 2025). "Would the presence of Ang II and EC injury in the initial stage of atherosclerosis activate the Pyk2/MCU pathway (further aggravating the progression of the disease)?" (PMID 34026753, 2021). "Finally, we found that MCU inhibitors alleviate lipid deposition and atherosclerosis induced by a high-fat, high-cholesterol diet both in vivo and in vitro." (PMID 41329250, 2025). "In this study, we identified the Pyk2/MCU pathway as a new regulator for atherosclerosis." (PMID 34026753, 2021). "We provide a body of evidence demonstrating that Pyk2/MCU may be a new target for inhibiting or reversing atherosclerosis." (PMID 34026753, 2021). "The inhibition of the Pyk2/MCU pathway which further modulates mitochondrial Ca2+ handling and apoptosis in atherosclerosis may confer a protective effect to the arteries against atherosclerosis." (PMID 34026753, 2021). "This study confirmed that rosuvastatin can inhibit the Pyk2/MCU pathway during atherosclerosis process in ApoE–/– mice with high-fat diet and HUVECs exposed to H2O2, further promoting mitochondrial function by maintaining the MMP, blocking intracellular Ca2+ influx, and reducing ROS release." (PMID 34026753, 2021). "In order to further examine whether the Pyk2/MCU pathway is a target for reversing atherosclerosis, we investigated the changes in Pyk2 and MCU at the transcript level and protein level on cell models." (PMID 34026753, 2021). "Pyk2/MCU regulates mitochondrial Ca2 + uptake, ROS production, mitochondrial membrane potential and apoptotic signaling, which affects the occurrence and development of atherosclerosis at a certain extent." (PMID 34026753, 2021). "Briefly, Pyk2/MCU regulates mitochondrial Ca2+ uptake, ROS production, mitochondrial membrane potential, and apoptotic signaling, which, in turn, affects the occurrence and development of atherosclerosis." (PMID 34026753, 2021). "Next, further verification would address the question whether inhibition of the Pyk2/MCU pathway is likely to be a new therapeutic target in the animal model for preventing the development of atherosclerosis." (PMID 34026753, 2021). "Furthermore, MCU inhibitors alleviate Western diet-induced atherosclerosis in ApoE-/- mice." (PMID 41329250, 2025). "Therefore, we consider that the activation of the Pyk2/MCU pathway has a crucial role in the EC injury process and may be involved in the pathological process of atherosclerosis." (PMID 34026753, 2021). "Aberrant activity of specific transporters—such as MCU complex-induced Ca2+ overload triggering mPTP opening in ischemia–reperfusion injury, VDAC1 oligomerization facilitating ROS leakage in atherosclerosis, and TRPC3/6-mediated Ca2+ influx promoting fibrosis—orchestrates hallmark features of CVDs." (PMID 40943400, 2025).
melanoma (5 papers, 2022 to 2025). A malignant, usually aggressive tumor composed of atypical, neoplastic melanocytes. "We observed that low levels of MCU expression were associated with melanoma and glioblastoma which increased overall survival and prolonged progression free survival (PFS) in patients having received immunotherapy PD-1 antibody." (PMID 37502961, 2023).
triple-negative breast carcinoma (5 papers, 2020 to 2025). An invasive breast carcinoma which is negative for expression of estrogen receptor (ER), progesterone receptor (PR), and human epidermal growth factor receptor 2 (HER2). "There is a high correlation between MCU expression and tumor growth and metastasis of triple-negative breast cancer; down-regulation of MCU attenuates tumor growth and invasiveness." (PMID 39866241, 2025). "Analysis specific to Triple-Negative Breast Cancer (TNBC) revealed a significant association between elevated TNBC levels and increased MCU transcript levels in both DNA microarray and RNA sequencing data." (PMID 38632642, 2024).
viral infection (5 papers, 2020 to 2025). "Viral infection can cause mitochondrial stress and release of mtDNA via Ca2+ uptake by the mitochondrial calcium uniporter (MCU) in a variety of cells." (PMID 37932533, 2023). "Ca2+ enters mitochondria via mitochondrial calcium uniporter (MCU), inducing mPTP opening and VDAC oligomerization under non-apoptotic stresses such as radiation, exposure to toxic substances, viral infection, and gene mutation." (PMID 40243714, 2025). "To clarify how MCU-dependent mitochondrial Ca2+ uptake contributes to T cell metabolism and function in vivo, we investigated mice with genetic deletion of MCU in T cells using models of autoimmunity and viral infection." (PMID 34987384, 2021). "Viral infections can promote mtDNA release via the mitochondrial calcium uniporter (MCU)." (PMID 39273156, 2024). "Furthermore, Tfh cell differentiation and GC B cell responses were intact in Mcufl/flCd4Cre mice, demonstrating that MCU is dispensable for ‘helper’ T cell responses during viral infection." (PMID 34987384, 2021). "Furthermore, upon viral infection, the mitochondrial calcium uniporter (MCU) complex amplifies the RLR signaling activation interacting with MAVS complexes at mitochondria and positively regulates the release of the proinflammatory cytokine IFN-β." (PMID 32182899, 2020).
Arrhythmia (4 papers, 2020 to 2025). Any cardiac rhythm other than the normal sinus rhythm. "This work indicates that MCU and CaMKII could be therapeutic targets for arrhythmia caused by metabolic abnormalities." (PMID 34497331, 2021). "In contrast, only one of the six hearts from MCU KO mice on HFD had inducible VT, indicating that this genotype is protected from arrhythmia caused by high-fat diet." (PMID 34497331, 2021).
ischemia (4 papers, 2016 to 2025). A hypoperfusion of the BLOOD through an organ or tissue caused by a PATHOLOGIC CONSTRICTION or obstruction of its BLOOD VESSELS, or an absence of BLOOD CIRCULATION. "Specifically, Ca2+ accumulates in neurons during ischemia and quickly enters mitochondria through the mitochondrial Ca2+ uniporter (MCU)." (PMID 40313775, 2025). "It was demonstrated that under ischemia/reperfusion injury, mitochondria accumulate significant amounts of calcium from the cytosol via mitochondrial calcium uniporter and blocking mitochondrial calcium uniporter was demonstrated to exert protective effects against ischemia/reperfusion injury." (PMID 27175924, 2016). "We hypothesized that since MCU inhibition prevents both Zn2+ and Ca2+ entrance into mitochondria, it likely causes a greater Ca2+ accumulation in the cytoplasm, which can lead to overactivation of NOX – another possible source of ROS after ischemia." (PMID 40313775, 2025). "During ischemia, a decrease in pH can inhibit proteins or stimulate their downregulation (* p < 0.05), such as a 3.6-fold decrease in the Na+/Ca2+ exchanger NCX1 and a 2.9-fold reduction in mitochondrial Ca2+ uniporter MCU in the 6-month-old hearts." (PMID 37189811, 2023).
prostate carcinoma (4 papers, 2015 to 2020). A carcinoma that arises from epithelial cells of the prostate gland. "For example, a recent study identified MCU down-regulation as a characteristic feature of some human colon and prostate cancer cells." (PMID 26156019, 2015). "Indeed, MCU expression is found to be upregulated in both colon and prostate cancer cells that show a reduced level of miR-25, and the overexpression of miR-25 in these cells downregulates MCU and increases cell sensitivity to apoptosis." (PMID 30555683, 2018).
brain injury (3 papers, 2019 to 2025). Acute and chronic (see also brain INJURIES, CHRONIC) injuries to the brain, including the cerebral hemispheres, CEREBELLUM, and brain STEM. "Brain injury promotes Ca2+ influx and mitochondrial Ca2+ loading via voltage-dependent anion channel 1 (VDAC1) and the mitochondrial Ca2+ uniporter (MCU), leading to mitochondrial dysfunction and cytochrome c-mediated apoptosis." (PMID 41284727, 2025).
breast tumors (3 papers, 2014 to 2017). "To determine whether our findings are clinically relevant, we examined the expression levels of MCU in breast tumor samples collected from 60 patients with different clinical and pathological characteristics." (PMID 29137386, 2017).
cardiomyopathy (3 papers, 2020 to 2025). A disease of the heart muscle or myocardium proper. "Additionally, Mendelian randomization (MR) analysis revealed a causal relationship between elevated levels of the SMDT1-encoded MCU regulator and increased risks of cardiovascular diseases, including coronary atherosclerosis, myocardial infarction, and cardiomyopathy." (PMID 40422231, 2025). "We show that adult MCU mutants exhibit cardiac remodeling resembling cardiomyopathy providing an animal model to assess MCU’s physiological roles in the heart." (PMID 33424641, 2020). "We have generated a zebrafish MCU mutant that survives to adulthood and exhibits dramatic cardiac phenotypes resembling cardiomyopathy and sinus arrest." (PMID 33424641, 2020). "Interestingly, while MCU activity appears to be dispensable for embryonic development in zebrafish, adult MCU mutants exhibited cardiac remodeling resembling cardiomyopathy along with functional defects including sinus arrest." (PMID 33424641, 2020).
gastric cancer (3 papers, 2022 to 2025). A primary or metastatic malignant neoplasm involving the stomach. "In our previous studies, through previous studies we found that MCU is highly expressed in gastric cancer tissues, and that high expression of MCU is associated with worse tumor staging and prognosis." (PMID 38737905, 2024). "Notably, elevated MCU expression has been reported in gastric cancer and is associated with poor clinical outcomes due to its impact on oxidative phosphorylation, the NAD+–NADH balance, the tricarboxylic acid cycle, and overall metabolic function." (PMID 41423315, 2025). "MCU acts as a channel for mitochondrial uptake of calcium ions, and how the high expression of MCU in gastric cancer has an impact on gastric cancer." (PMID 38737905, 2024). "Immunohistochemical staining was utilized to detect the expression of the MCU protein in the tumor tissues of 205 patients with gastric cancer." (PMID 38737905, 2024). "Through data analysis, we found that MCU expression changes may widely affect mitochondrial function in gastric cancer patients, including energy production and a variety of bio anabolic processes including the synthesis and metabolism of amino acids, nucleotides, proteins, lipids, and NAD+/NADH." (PMID 38737905, 2024).
glioma (3 papers, 2024 to 2026). A benign or malignant brain and spinal cord tumor that arises from glial cells (astrocytes, oligodendrocytes, ependymal cells). "This proves that MCU plays an important role in regulating the migration of glioma cells, providing a new perspective." (PMID 38356708, 2024). "Taken together, these findings indicate that as a potent regulator, MCU facilitates the migration of glioma cells." (PMID 38356708, 2024). "First, in a bioinformatics search and immunohistochemical analysis of glioma samples, the expression of MCU increased with the malignant degree of glioma." (PMID 38356708, 2024). "The signalling pathway and mechanism involved in the occurrence and development of glioma are very complicated, and there are also complex and close relationships among autophagy, p38MAPK and MCU." (PMID 38356708, 2024). "Collectively, our findings suggest that MCU regulates glioma cell migration through modulation of the p38 MAPK signalling pathway." (PMID 38356708, 2024). "Our analysis revealed that MCU and p38 were significantly overexpressed in glioma tissues compared to normal brain tissue." (PMID 38356708, 2024). "In this work, we found that MCU and p38 expression were positively correlated with glioma grade and the degree tumour progression." (PMID 38356708, 2024). "On the contrary, when MCU is overexpressed or agonist-treated, the migration of glioma cells is promoted." (PMID 38356708, 2024). "Mitochondrial Calcium Uniporter (MCU) plays an important role in regulating glioma progression." (PMID 38356708, 2024). "The expression of MCU increased gradually from grade II to grade IV glioma." (PMID 38356708, 2024). "When MCU is knocked down or inhibited, the migration of glioma cells is specifically inhibited." (PMID 38356708, 2024). "This suggests that MCU may be a potential target for glioma treatment." (PMID 38356708, 2024). "Furthermore, the levels of MCU expression in gliomas from grade II to IV were examined by IHC." (PMID 38356708, 2024). "Through the analysis of the China Glioma Genome Atlas (CGGA) database, it was found that there is a certain positive correlation between the expression of MCU and the expression of glioma cell markers, suggesting that MCU may be highly expressed in glioma cells." (PMID 38356708, 2024). "In addition, the mechanism by which MCU regulates autophagy in glioma cell migration was clarified, providing a new theoretical basis and molecular therapeutic target for further understanding the influence of MCU on glioma." (PMID 38356708, 2024). "In summary, our results show that MCU regulates TFEB-mediated autophagy and promotes the migration of glioma cells through p38." (PMID 38356708, 2024). "The expression of Mitochondrial Calcium Uniporter (MCU) and p38 correlated positively with glioma grading and tumor progression." (PMID 38632642, 2024). "Targeting the MCU-MECOM axis induces metabolic suppression and reduces glioma cell viability." (PMID 42212314, 2026). "Thus, MCU promotes glioma cell migration by activating autophagy in a p38/TFEB pathway-dependent manner, which provides a theoretical basis for new therapeutic targets for gliomas." (PMID 38356708, 2024).
myocardial infarction (3 papers, 2016 to 2025). Gross necrosis of the myocardium, as a result of interruption of the blood supply to the area, as in coronary thrombosis. "Importantly, blocking the MCU complex with Ru360 limited the myocardial infarction size, whereas activating the MCU complex nullified the protective effects of HINT2 on infarction expansion." (PMID 34914018, 2021). "Thus, this new mitochondrial cAMP/sACt/Epac1/MCU pathway might have therapeutic implications to regulate cell death in cardiac pathologies, such as HF and/or myocardial infarction." (PMID 27100892, 2016).
myocardial ischemia (3 papers, 2020 to 2025). A disorder of cardiac function caused by insufficient blood flow to the muscle tissue of the heart. "Concurrently, in vivo, myocardial ischemia led to a significant increase in the calcium regulatory proteins cyclophilin D (CypD) and mitochondrial Ca2+ uniporter (MCU) on MAMs, while sigma-1 receptor (Sig-1R) and neurite outgrowth inhibitor B (NOGO-B) were significantly reduced." (PMID 40799639, 2025). "Histidine triad nucleotide-binding 2 (HINT2) has been reported to modulate [Ca2+]m via the MCU complex, and our previous work demonstrated that HINT2 improved cardiomyocyte survival and preserved heart function in mice with cardiac ischemia." (PMID 34914018, 2021).
Nephropathy (3 papers, 2018 to 2023). A nonspecific term referring to disease or damage of the kidneys. "Although the pathophysiological role of MCU in kidney diseases remains largely unclear, a previous report has shown that an MCU inhibitor, ruthenium red, decreases proteinuria and attenuates podocyte foot process effacement in adriamycin-induced nephropathy." (PMID 36454699, 2023). "The podocyte-protective effects of an MCU inhibitor were further investigated in rats with Adriamycin-induced nephropathy." (PMID 29907098, 2018).
ovarian carcinoma (3 papers, 2015 to 2024). A malignant neoplasm originating from the surface ovarian epithelium. "High levels of MCU expression were also observed in ovarian cancer, and its silencing reduced proliferation and migration of ovarian cancer cells, possibly due to reduced ROS production." (PMID 38632642, 2024). "High levels of MCU expression were also found in ovarian cancer, and its silencing reduces ovarian cancer cell proliferation and migration." (PMID 37759703, 2023). "Interestingly, Ru360 (an inhibitor of the mitochondrial calcium uniporter) reversed mitochondrial changes and restored cell survival in HEY ovarian carcinoma cells treated with iron." (PMID 25697096, 2015).
pancreatic ductal adenocarcinoma (3 papers, 2023 to 2025). An infiltrating adenocarcinoma that arises from the epithelial cells of the pancreas. "Pancreatic ductal adenocarcinoma (PDAC) studies demonstrate mitochondrial calcium uniporter (MCU) regulates cystine metabolic reprogramming through the Keap1–Nrf2–SLC7A11 axis." (PMID 40919133, 2025).
autoimmune disease (2 papers, 2025). A disorder resulting from loss of function or tissue destruction of an organ or multiple organs, arising from humoral or cellular immune responses of the individual to their own tissue constituents. "This study demonstrates that the mitochondrial Ca2+ uniporter (MCU) complex is critical for T-cell function, emphasizing the potential of targeting mCa2+ homeostasis as a therapeutic approach for managing autoimmune diseases." (PMID 39623165, 2025). "T-cell specific MCU inhibition is thus a potential tool for targeting autoimmune disorders." (PMID 39623165, 2025). "T cell-specific MCU knockout in an experimental autoimmune encephalomyelitis (EAE) model alleviated neuroinflammation by suppressing mitochondrial calcium overload, suggesting that MCU is a promising therapeutic target for autoimmune diseases." (PMID 40989817, 2025).
Autoimmunity (2 papers, 2021 to 2025). The occurrence of an immune reaction against the organism's own cells or tissues. "Based on these findings, we proceeded in evaluating the role of MCU in T-cell-mediated autoimmunity." (PMID 39623165, 2025). "Our findings suggest that T-cell-specific inhibition of MCU could be harnessed as an efficient strategy to treat T-cell-mediated autoimmunity." (PMID 39623165, 2025). "Collectively, these data demonstrate that, despite attenuating mitochondrial Ca2+ uptake and elevating cytosolic Ca2+ levels after antigen receptor stimulation, MCU is largely dispensable for T cell-mediated immune responses in vitro and in models of autoimmunity and persistent viral infection." (PMID 34987384, 2021).
colon adenocarcinoma (2 papers, 2018 to 2023). "However, the role of MCU complex in colon adenocarcinoma (COAD) remains unclear." (PMID 37056383, 2023).
endometrial cancer (2 papers, 2024 to 2025). Primary or metastatic malignant neoplasm involving the endometrium (mucous membrane that lines the endometrial cavity). "Mitochondrial calcium uniporter (MCU) is markedly upregulated in endometrial cancer tissue compared to normal endometrium, with elevated MCU levels strongly correlating with higher histological grade, deeper myometrial invasion, and lymph node metastasis." (PMID 41226294, 2025). "MCU upregulation enhances mitochondrial activity and promotes clone formation and migration of endometrial cancer cells; it also interacts with VDAC1 to enhance regulation of mitochondrial calcium uptake and promote endometrial cancer progression." (PMID 38711526, 2024).